PI4K2B (phosphatidylinositol 4-kinase type 2 beta)
Description:
Together with PI4K2A and the type III PI4Ks (PIK4CA and PIK4CB) it contributes to the overall PI4-kinase activity of the cell. This contribution may be especially significant in plasma membrane, endosomal and Golgi compartments. The phosphorylation of phosphatidylinositol (PI) to PI4P is the first committed step in the generation of phosphatidylinositol 4,5-bisphosphate (PIP2), a precursor of the second messenger inositol 1,4,5-trisphosphate (InsP3). Contributes to the production of InsP3 in stimulated cells and is likely to be involved in the regulation of vesicular trafficking.
Synonyms: PI4KIIB; FLJ11105; PIK42B
Tractability: Small molecule: a structure with a bound ligand is known; a high-quality ligand is known. Antibody: UniProt places it where antibodies can reach, with high confidence; its Gene Ontology location is reachable by antibodies, with high confidence. PROTAC: ubiquitination databases record sites on it; its protein half-life has been measured; a small molecule that binds it is known.
Target class: Enzyme; Transferase
Gene: Protein-coding gene on chromosome 4 (25,160,663 to 25,280,542, forward strand). Ensembl gene ENSG00000038210.
Subcellular location: Cytoplasm, cytosol; Golgi apparatus membrane; Endoplasmic reticulum membrane; Cell membrane; Early endosome membrane
Subcellular location (Human Protein Atlas): Cytosol
Pathways (Reactome):
Metabolism: Synthesis of PIPs at the ER membrane; Synthesis of PIPs at the Golgi membrane; Synthesis of PIPs at the early endosome membrane; Synthesis of PIPs at the plasma membrane
Gene Ontology:
Molecular function: 1-phosphatidylinositol 4-kinase activity
Biological process: phosphatidylinositol phosphate biosynthetic process; endosome organization; Golgi organization; phosphatidylinositol biosynthetic process
Cellular component: cytosol; early endosome membrane; endoplasmic reticulum membrane; Golgi membrane; membrane; plasma membrane; endosome; trans-Golgi network
Genetic constraint (gnomAD): Loss-of-function variants: 20 observed, 19.95 expected, observed/expected ratio (o/e) 1, 90% interval 0.7 to 1.46. The upper end of that interval is the gene's LOEUF score, 1.46, which puts it in group 6 of 6, group 1 being the genes least tolerant of losing a copy. Missense variants: 339 observed, 292.18 expected, observed/expected ratio (o/e) 1.16, 90% interval 1.06 to 1.27. Synonymous variants: 150 observed, 121.23 expected, observed/expected ratio (o/e) 1.24, 90% interval 1.08 to 1.42.
Homologues: Orthologues: chimpanzee PI4K2B (99% identical), macaque PI4K2B (93% identical), pig PI4K2B (85% identical), dog PI4K2B (83% identical), guinea pig PI4K2B (82% identical), rat Pi4k2b (80% identical), mouse Pi4k2b (79% identical), rabbit PI4K2B (77% identical), tropical clawed frog pi4k2b (71% identical), zebrafish pi4k2b (68% identical), Drosophila melanogaster Pi4KIIalpha (55% identical), Caenorhabditis elegans ZC8.6 (47% identical). Paralogues in human: PI4K2A (58% identical).
Diseases named in the same sentence as PI4K2B in open-access papers:
PI4K2B is named in the same sentence as 17 diseases in open-access papers, as found by Europe PMC text mining. Sharing a sentence is not in itself a finding about the gene and the disease. The quoted sentences say what the papers report.
cannabis dependence (2 papers, 2019 to 2021). Physical and psychological dependence on the drug cannabis. "Another GWAS study has associated a PI4K2B SNP with cannabis dependence, which in turn is associated with increased risk of schizophrenia, while PI4K2B has also been identified as a candidate gene in schizophrenia on a study on Scottish population cohort." (PMID 31507376, 2019).
schizophrenia (2 papers, 2009 to 2019). A major psychotic disorder characterized by abnormalities in the perception or expression of reality. "This study examined PI4K2B as a possible genetic risk factor in bipolar disorder or schizophrenia, by two approaches." (PMID 19539307, 2009). "This study identified association between a haplotype in PI4K2B, which withstood gene-wide permutation testing, and schizophrenia, but not bipolar disorder." (PMID 19539307, 2009).
attention deficit-hyperactivity disorder (1 paper, 2021). A disorder characterized by a marked pattern of inattention and/or hyperactivity-impulsivity that is inconsistent with developmental level and clearly interferes with functioning in at least two settings (e.g. at home and at school). "PI4K2B contributes to the overall PI4-kinase activity of the cell and is associated with attention deficit hyperactivity disorder (ADHD), logical memory and abnormality of neuronal migration." (PMID 34384432, 2021).
bipolar disorder (1 paper, 2009). A disorder of the brain that causes unusual shifts in mood, energy, activity levels and the ability to carry out day-to-day tasks. "PI4K2B is a strong functional candidate as it is a member of the phosphatidylinositol pathway, which is targeted by lithium for therapeutic effect in bipolar disorder." (PMID 19539307, 2009). "This study showed that there was no direct evidence for a role of PI4K2B in susceptibility to bipolar disorder from expression studies in lymphoblastoid cell lines." (PMID 19539307, 2009). "PI4K2B was a worthy candidate gene for bipolar disorder in many respects." (PMID 19539307, 2009).
colorectal tumours (1 paper, 2025). "In gene analyses, PI4K2B associated with survival in patients with distal cancers (P = 2.1 × 10–6) and increased PI4K2B expression in colorectal tumours was associated with improved survival (P = 9.6 × 10–5)." (PMID 39827162, 2025). "We sought an association between PI4K2B expression levels in colorectal tumours and survival in 597 unrelated patients with CRC from The Human Protein Atlas (THPA)." (PMID 39827162, 2025). "Interestingly, we found that higher PI4K2B expression in tumour tissue was associated with improved survival in patients with colorectal tumours from THPA." (PMID 39827162, 2025). "We investigated the relationship between Phosphatidylinositol 4-Kinase Type 2 Beta (PI4K2B) expression in colorectal tumours and survival in 597 patients from The Human Protein Atlas (THPA)." (PMID 39827162, 2025).
diabetes (1 paper, 2024). "We used machine learning to identify six key genes closely associated with vascular aging in diabetes: TFB1M, FOXRED2, LY75, DALRD3, PI4K2B, and NDOR1." (PMID 38809515, 2024). "Using bioinformatics and machine learning techniques, we identified six key genes that are closely associated with vascular aging in diabetes: TFB1M, FOXRED2, LY75, DALRD3, PI4K2B, and NDOR1." (PMID 38809515, 2024). "Dysregulation of PI4K2B could disrupt important cellular processes, such as vesicle transport and signal transduction, contributing to vascular dysfunction in diabetes." (PMID 38809515, 2024). "The expression of TFB1M, FOXRED2, DALRD3, PI4K2B, and NDOR1 was negatively correlated with vascular aging in diabetes, while LY75 expression was positively correlated." (PMID 38809515, 2024).
tumor (3 papers, 2023 to 2025). "Among all the PI4P producing enzymes high tumor PI4KA and PI4K2B expression is associated with poor overall survival in mHSPC patients, whereas the expression of other two PI4P producing enzymes PI4KB and PI4K2A do not have statistical significance." (PMID 37996444, 2023). "Next, we evaluated the expression of LIMK2 and PI4K2B in SCLC tumor and normal tissues by using GSE40275 and GSE60052 datasets." (PMID 37189142, 2023). "On the contrary, these previous studies have indicated that PI4K2B may function as a tumor suppressor to inhibit tumor invasion." (PMID 37189142, 2023).
cancer (2 papers, 2023 to 2025). A tumor composed of atypical neoplastic, often pleomorphic cells that invade other tissues. "PI4K2B, however, functions as a negative regulator of cancer cell invasion and is frequently deleted or downregulated in human cancers." (PMID 36757799, 2023).
PI4K2B also shares sentences with these, for which no sentence is quoted: COVID-19 (1 paper); cyst (1); Huntington disease (1); liver cancer (1); lung carcinoma (1); neurodegenerative disease (1); nicotine dependence (1); oculocerebrorenal syndrome (1); rectal tumours (1).